SNHG4 (small nucleolar RNA host gene 4)
Diseases named in the same sentence as SNHG4 in open-access papers (continued):
Sharing a sentence is not in itself a finding about the gene and the disease.
endometriosis (5 papers, 2021 to 2023). The growth of functional endometrial tissue in anatomic sites outside the uterine body. "An association was observed between SNHG4 gene expression and rASRM classification in the endometriosis group." (PMID 36672893, 2023). "The high expression of SNHG4 was significantly associated (p = 0.031) with advanced stages of endometriosis." (PMID 36672893, 2023). "According to our pilot study, elevated SNHG4 expression levels may be associated with endometriosis." (PMID 36672893, 2023). "The expression of SNHG4 in patients with stage 1–2 endometriosis was statistically significantly lower compared to patients with stage 3–4 endometriosis." (PMID 36672893, 2023). "Statistically significantly higher SNHG4 expression was observed in cases of endometriosis compared to controls." (PMID 36672893, 2023). "This suggests that SNHG4 is involved in the growth of endometrial cancer cells as well as endometriosis, a normal tissue." (PMID 37189636, 2023). "Because of this, it is known that SNHG4 promotes the growth of several cancer cells and endometriosis cells in vivo." (PMID 37189636, 2023). "Our statistical analysis showed a significant correlation of SNHG4 expression levels with endometriosis." (PMID 36672893, 2023). "Recent studies on endometriosis have highlighted lncRNA SNHG4, whose impaired expression can be observed in many cancers." (PMID 36672893, 2023). "A statistically significant relationship between expression level and SNHG4 was found in relation to The Revised American Society for Reproductive Medicine classification of endometriosis, 1996, in the group of patients with endometriosis." (PMID 36672893, 2023). "Recently, attention has been drawn to SNHG4, which is incorrectly expressed in various human diseases, including endometriosis." (PMID 36672893, 2023). "The results presented in this paper regarding the analysis of SNHG4 reveal the existence of certain relationships between its expression and endometriosis." (PMID 36672893, 2023). "In the present work, we presented an analysis of SNHG4 expression in patients with endometriosis compared to the control group." (PMID 36672893, 2023). "Another study revealed that the up‐regulated lncRNA SNHG4 promoted the proliferation of endometrial stromal cells via regulation of c‐Met and was mediated by miR‐148a‐3p in endometriosis." (PMID 33372387, 2021). "Second, Liu and colleagues studied the lncRNA small nucleolar host gene 4 (SNHG4) in a heterologous mouse model of endometriosis." (PMID 34638965, 2021). "The expression level of SNHG4 correlated with the stage of endometriosis." (PMID 36672893, 2023). "Recent studies have highlighted lncRNA SNHG4 (small nucleolar RNA host gene 4), which may be important in the context of endometriosis." (PMID 36672893, 2023). "The state of knowledge we currently have concerning SNHG4 in endometriosis remains limited." (PMID 36672893, 2023). "SNHG4 expression has been analyzed in tumors and endometriosis." (PMID 36672893, 2023). "As presented in the introduction, SNHG4 transcription plays an important role in key biological processes occurring in cancer and in non-cancerous diseases such as endometriosis." (PMID 36672893, 2023). "In summary, the results of in vivo studies showed that SNHG4 not only plays a tumorigenic role in some cancers but also promotes the growth of intimal tissues in non-tumour diseases such as endometriosis." (PMID 34717631, 2021). "According to the available literature, SNHG4 expression has not yet been studied in endometriosis." (PMID 36672893, 2023). "The authors postulated that SNHG4 might upregulate proto-oncogene expression, in particular MET, via the suppression of miR-148a-3p, to promote the increased growth of endometrial tissue outside the uterine cavity and endometriosis lesions." (PMID 34638965, 2021).
Cerebral ischemia (3 papers, 2022 to 2024). Restriction of arterial blood supply to the brain associated with insufficient oxygenation to support the metabolic requirements of the tissue. "LncRNA Small Nucleolar RNA Host Gene 4 (SNHG4) emerges as a novel lncRNA associated with a myriad of human pathologies, including various cancers, neonatal pneumonia, and cerebral ischemia–reperfusion injury." (PMID 38831471, 2024). "SNHG4 has also been shown to have the anti-inflammatory effect in microglia after cerebral ischemia–reperfusion injury." (PMID 36140769, 2022). "SNHG4 regulates STAT6 and suppresses inflammation by adsorbing miR-449c-5p in microglia during cerebral ischemia-reperfusion injury." (PMID 36275741, 2022). "Therefore, SNHG4 regulates STAT6 and inhibits inflammation by adsorbing miR-449c-5p in microglia during cerebral ischemia-reperfusion injury." (PMID 36275741, 2022).
glioma (3 papers, 2020 to 2025). A benign or malignant brain and spinal cord tumor that arises from glial cells (astrocytes, oligodendrocytes, ependymal cells). "While, the function of SNHG4 on migration and the underlying mechanism of SNHG4 in glioma progression is still unclear." (PMID 39951205, 2025). "Mechanically, SNHG4 participated in the progression of glioma through the miR-367-3p/MYO1B axis, which was a novel signaling pathway of SNHG4." (PMID 39951205, 2025). "Subsequently, GEPIA dataset analysis revealed that high expression of SNHG4 in glioma tissues had shorter over survival than those with low expression of SNHG4." (PMID 39951205, 2025). "In summary, this study verified the biological roles of SNHG4 in glioma cells in vitro and in zebrafish xenograft model, especially the function of migration, which is the first time confirmed." (PMID 39951205, 2025). "Our study reveals that SNHG4 promotes the proliferation, migration of glioma via regulating miR-367-3p/MYO1B axis." (PMID 39951205, 2025). "In our study, zebrafish xenograft models were used as an in vivo model to verify the roles of SNHG4 on cell growth and metastasis of glioma." (PMID 39951205, 2025). "In our study, zebrafish xenograft model was used as the in vivo model to verify the biological roles and the results showed that knocking down of SNHG4 inhibited the growth and metastasis of glioma cells in vivo." (PMID 39951205, 2025). "To verify the biological roles of SNHG4 in glioma cells, we transfected small interference RNA (siRNAs-SNHG4) to knockdown the expression of SNHG4 in Ln229 and U251 cells, and over-expression plasmids (pcDNA3.1, pcDNA3.1-SNHG4) to upregulate SNHG4 expression." (PMID 39951205, 2025). "Meanwhile, as the in vivo tool, zebrafish xenograft model was used to verify the functions of SNHG4 in glioma cells." (PMID 39951205, 2025). "Rescue assays showed that knockdown of SNHG4 inhibited glioma cell proliferation, migration, while the inhibitory effects were impaired by inhibiting miR-367-3p or overexpression of MYO1B." (PMID 39951205, 2025). "And we have proved that SNHG4 promoted cell migration of glioma in vitro and in vivo for the first time." (PMID 39951205, 2025). "In this study, the results showed that SNHG4 was highly expressed in glioma tissues and cells lines." (PMID 39951205, 2025). "In this study, by analysis of the public database, we found that SNHG4 was upregulated in multiple cancer tissues, including glioma." (PMID 39951205, 2025). "Functionally, rescue experiments were performed and the results showed that the inhibitory effect of SNHG4 knockdown was impaired by inhibition of miR-367-3p on cell proliferation and migration of glioma." (PMID 39951205, 2025). "All these data indicated that SNHG4 promoted the progression of glioma." (PMID 39951205, 2025). "In conclusion, our study elucidates mechanism that SNHG4 promotes progression of glioma through miR-367-3p/MYO1B axis, which may contribute to find the potential diagnostic and therapeutic target of glioma patients." (PMID 39951205, 2025). "The SNHG4/miR-367-3p/MYO1B axis might provide a novel approach for the treatment of glioma patients, which might be used as the potential prognostic and therapeutic biomarkers." (PMID 39951205, 2025). "In our research, the main purpose was to explore the roles and mechanism of SNHG4 in glioma." (PMID 39951205, 2025). "While, overexpression of SNHG4 enhanced these functions of glioma cells in vitro." (PMID 39951205, 2025). "Furthermore, the rescue experiments showed that the inhibition of miR-367-3p or the expression of MYO1B partially rescue the inhibition effects of SNHG4 in glioma cells." (PMID 39951205, 2025). "To determine whether SNHG4 promoted the progression of glioma through miR-367-3p, we performed rescue experiment." (PMID 39951205, 2025). "Furthermore, we detected the expression of SNHG4 by qRT-PCR in glioma cell lines (Ln229, U251 and U87) and the human normal brain astrocyte cell line (SVG)." (PMID 39951205, 2025).
glioma (continued). "To investigate that SNHG4 plays roles in the progression of glioma through MYO1B-regulated pathway, we first detected the expression of MYO1B after knocking down SNHG4 in Ln229 and U251 cells in mRNA and protein levels by qRT-PCR and western blot assays." (PMID 39951205, 2025). "The data showed that the SNHG4 expression was upregulated in many cancers compare with normal tissues, including glioma." (PMID 39951205, 2025).
neuroblastoma (3 papers, 2020 to 2025). Neuroblastoma (NB) is the most common solid, extracranial childhood tumor. "SNHG4 silencing increases the expression of pro-apoptotic proteins such as Bax and caspase-3, thereby promoting neuroblastoma cell apoptosis." (PMID 34717631, 2021). "SNHG4 increases neuroblastoma proliferation, migration, and invasion." (PMID 39735673, 2025). "In addition, in an in vivo study of neuroblastoma, researchers found that SNHG4 promotes tumour cell growth, invasion, and migration, especially lung metastasis, and induces apoptosis." (PMID 34717631, 2021).
renal cell carcinoma (3 papers, 2021 to 2025). "The upregulation of SNHG4 is associated with lymph node involvement, distant metastasis, and reduced overall survival for renal cell carcinoma patients." (PMID 40286292, 2025). "Knockdown SNHG4 may inhibit the growth of tumours including renal cell carcinoma (RCC), colorectal cancer (CRC), cervical cancer (CC), lung cancer, and non-small cell lung cancer (NSCLC)." (PMID 36672893, 2023).
acute myeloid leukaemia (2 papers, 2021 to 2023). "Nevertheless, SNHG4 was downregulated in acute myeloid leukemia cells, and inhibited the proliferation via modulating the miR‐10a/PTEN axis." (PMID 36565037, 2023).
diabetic retinopathy (2 papers, 2021 to 2023). "In another study on diabetic retinopathy, researchers found that SNHG4 upregulates the expression of Oxr1 by sponging miR-200b and thus inhibits ARPE-19 cell apoptosis." (PMID 34717631, 2021).
glioblastoma (2 papers, 2020 to 2021). The most malignant astrocytic tumor (WHO grade IV). "In addition, SNHG4 can function as a ceRNA, sponge miR-138 to upregulate c-Met, sponge miR-204-5p to upregulate RUNX2, and then promote glioblastoma cell and RCC cell proliferation." (PMID 34717631, 2021).
lymph node metastasis (2 papers, 2023 to 2025). "SNHG4 expression exhibited significant correlation with the lymph node metastasis (p = 0.008), tumor size (p = 0.004), as well as TNM stages (p = 0.002), with no significant relation to age, sex as well as histological grades." (PMID 39735673, 2025). "In addition, univariate proportional hazard analysis with lymph node metastasis (univariate hazard ratio [HR] = 8.138 (2.153–30.757), p = 0.002) showed that high expression of SNHG4 and lymph node metastasis were predictors." (PMID 37189636, 2023).
chronic obstructive pulmonary disease (1 paper, 2024). A chronic and progressive lung disorder characterized by the loss of elasticity of the bronchial tree and the air sacs, destruction of the air sacs wall, thickening of the bronchial wall, and mucous accumulation in the bronchial tree. "The long non-coding RNA (lncRNA) Small Nucleolar RNA Host Gene 4 (SNHG4) has been demonstrated to be significantly downregulated in various inflammatory conditions, yet its role in chronic obstructive pulmonary disease (COPD) remains elusive." (PMID 38831471, 2024).
endometrial cancer (1 paper, 2023). Primary or metastatic malignant neoplasm involving the endometrium (mucous membrane that lines the endometrial cavity). "Then, we first showed that high expression of SNHG4 was strongly associated with tumor stage, lymph node metastasis, and short overall survival, suggesting that this lncRNA SNHG4 exerts a positive regulatory effect on the clinical progression of endometrial cancer." (PMID 37189636, 2023). "In this study, we tried to confirm the expression of lncRNA SNHG4 as a predictive marker for endometrial cancer and to study its relationship with transcription factor SP-1." (PMID 37189636, 2023). "In this study, we confirmed that the lncRNA SNHG4 is overexpressed in the blood of endometrial cancer patients using RT-PCR analysis." (PMID 37189636, 2023). "mRNA levels were evaluated after knock-down of SNHG4 in two endometrial cancer cell lines, and it was confirmed that the expression of E-cadherin increased and, conversely, the expression of β-catenin, N-cadherin, SP-1, and Wnt5β decreased." (PMID 37189636, 2023). "Western blot confirmed that knock-down of SNHG4 in two endometrial cancer cell lines regulates G1 arrest by CyclinD1, CDK4, and p27." (PMID 37189636, 2023). "Kaplan–Meier survival analysis showed that endometrial cancer patients with low SNHG4 expression had longer progression-free survival than did patients with high SNHG4 expression (p = 0.020, respectively)." (PMID 37189636, 2023). "In this study, it was confirmed that cancer cell growth was inhibited by knock-down of SNHG4 in a xenograft mouse model of endometrial cancer cells." (PMID 37189636, 2023). "To confirm the role of SNHG4 in endometrial cancer, we experimented with the expression of SNHG4 in the endometrial cancer cell lines." (PMID 37189636, 2023). "In this study, we confirmed that the lncRNA SNHG4 is upregulated in endometrial cancer and correlates with lower survival rates in endometrial cancer patients." (PMID 37189636, 2023). "In summary, these data demonstrate that in endometrial cancer, SNHG4 is regulated by SP-1 at the transcriptional level and is indirectly associated with SNHG4." (PMID 37189636, 2023). "In this study, it was confirmed that the expression of CyclinD1 and Cdk4 was decreased due to SNHG4 knock-down in endometrial cancer cells, and the arrest of the G1 phase was confirmed." (PMID 37189636, 2023). "Our study demonstrates that the lncRNA SNHG4 can act as a regulator of endometrial cancer cell progression." (PMID 37189636, 2023). "To further understand the clinical relevance of SNHG4 expressions in endometrial cancer serum, we divided all 100 patients with high SNHG4 expression (n = 73) and patients with low SNHG4 expression (n = 27)." (PMID 37189636, 2023). "We investigated whether the expression of SNHG4 in endometrial cancer serum (n = 100) and normal serum (n = 26) is related to the clinical and pathological characteristics of endometrial cancer." (PMID 37189636, 2023). "We found in this study that SNHG4/SP-1 plays an important role in endometrial cancer progression and may be used as a potential therapeutic and prognostic biomarker for endometrial cancer." (PMID 37189636, 2023). "We further performed a loss-of-function assay to determine the potential function of SNHG4 and found that knockdown of SNHG4 markedly inhibited the proliferation, migration, and invasion of endometrial cancer cells, indicating that SNHG4 inhibits endometrial cancer cells." (PMID 37189636, 2023). "In addition, it was clinically confirmed that SNHG4 is a biomarker that can predict stage and lymph node metastasis in endometrial cancer." (PMID 37189636, 2023). "Knock-down of SNHG4 significantly reduced cell proliferation, colonization, migration, and invasion in vitro, as well as modulating the cell cycle and reduced tumor growth of endometrial cancer in vivo." (PMID 37189636, 2023).
endometrial cancer (continued). "Additionally, to evaluate the relationship between SP-1 and SNHG4, one of the transcription factors regulating lncRNA, the expression of SP-1 was evaluated in endometrial cancer cells in which SNHG4 was knocked down, and it was confirmed that the expression of SP-1 was reduced." (PMID 37189636, 2023). "In addition, β-catenin mobilizes and attenuates the relevant mesenchymal phenotype It was confirmed that the expression of E-cadherin increased in endometrial cancer cells in which SNHG4 was knocked down, and the expression of N-cadherin, β-catenin, and Wnt5β decreased." (PMID 37189636, 2023). "Thus, SNHG4 may contribute to the endometrial cancer cell phenotype through activation of EMT and SP-1 signaling." (PMID 37189636, 2023). "Although research on SNHG4 in human diseases is increasing, there are no research reports on endometrial cancer as of yet." (PMID 37189636, 2023). "The expression of SNHG4 in endometrial cancer serum was more than 20 times higher than in noncancerous serum (p = 0.00001)." (PMID 37189636, 2023).
Hypertension (1 paper, 2022). The presence of chronic increased pressure in the systemic arterial system. "The greatest number of expression correlations was found between the DEGs associated with hypertension and LOC100910237, RGD1562890, Snhg4, and Tnxa-ps1." (PMID 36140769, 2022). "Expression of four lncRNAs (Snhg4, LOC100910237, RGD1562890, and Tnxa-ps1) correlated with transcription levels of many hypothalamic genes differentially expressed between ISIAH and WAG rats (DEGs), including genes associated with the behavior/neurological phenotype and hypertension." (PMID 36140769, 2022).
lipid metabolism disorder (1 paper, 2025). "SNHG4 overexpression mitigated the lipid metabolism disorder and inflammation triggered by FFA, while this effect was suppressed by silencing XIAP." (PMID 41084767, 2025).
lung injury (1 paper, 2023). "SNHG4 inhibited METTL3‐mediated m6A level of STAT2 mRNA, which resulted in the alleviated LPS‐induced inflammatory lung injury." (PMID 36565037, 2023).
myocardial infarction (1 paper, 2022). Gross necrosis of the myocardium, as a result of interruption of the blood supply to the area, as in coronary thrombosis. "Long noncoding RNAs (lncRNAs), including some members of small nucleolar RNA host gene (SNHG), are important regulators in myocardial injury, while the role of SNHG4 in myocardial infarction (MI) is rarely known." (PMID 36545243, 2022).
neuropathic pain (1 paper, 2020). Chronic pain caused by damage to nerve fibers. "This suggested that SNHG4 might serve as a new target for treating neuropathic pain in humans, which can provide a new intervention strategy for neuropathic pain patients." (PMID 32454787, 2020).
prostate tumor (1 paper, 2023). "Data from TCGA databases suggested that SNHG4 expression was significantly correlated with the expression of RRM2, EZH2, AURKA and TK1 in prostate tumor samples (p < 0.01)." (PMID 37596700, 2023).
systemic lupus erythematosus (1 paper, 2024). An autoimmune multi-organ disease typically associated with vasculopathy and autoantibody production. "For example, lncRNAs, such as Hotair, LUST, anti-NOS2A, MEG9, SNHG4, TUG1, and NEAT1, have been found to be highly expressed in rheumatoid arthritis, while the expression of lnc-HSFY2–3:3 and lnc-SERPINB9–1:2 is reduced in systemic lupus erythematosus (SLE)." (PMID 38473997, 2024).